CXCR2 (C-X-C motif chemokine receptor 2)
Diseases named in the same sentence as CXCR2 in open-access papers (continued):
Sharing a sentence is not in itself a finding about the gene and the disease.
COVID-19 (continued). "In addition to the chemokine receptors predominantly expressed on CD56brightCD16– NK cells, we found high expression of CXCR2 on peripheral blood CD56dimCD16+ NK cells both in healthy controls and COVID-19 patients." (PMID 35371005, 2022). "Although most blood neutrophils stained positive for CXCR1 and CXCR2, the relative expression levels of these chemoattractant receptors were significantly lower on blood neutrophils from patients with COVID-19 compared with blood neutrophils from healthy controls." (PMID 34793331, 2022). "We also observed significant up-regulation of CD66b, CD177, CD11b, CXCR4, CD147 (the receptor that binds the spike protein of SARS-CoV-2), and CD63 in mature neutrophils from COVID-19 patients compared to healthy controls, as well as significant down-regulation of CXCR2." (PMID 34548411, 2021). "In this context, CXCR2 antagonists, including several compounds in clinical development, could play a beneficial role in the treatment of patients with severe COVID-19." (PMID 33780519, 2021). "Expression levels of the receptor of MCP-1, C-C motif receptor 2 (CCR2); the receptor for IP-10, chemokine (C-X-C motif) receptor 3 (CXCR3); and the receptor for IL-8, CXCR2 were assessed in the PBMCs from severe or mild COVID-19 patients compared to those from healthy controls." (PMID 33413449, 2021). "They suggest that CXCR2 antagonists, in particular IL-8 antagonists, could be promising candidates for the treatment of patients with severe COVID-19." (PMID 33780519, 2021). "Therefore, an overall increase in neutrophils CCRL2 expression could significantly impair the proper CXCR2-mediated neutrophil trafficking in COVID-19 patients, thus resulting in a neutrophil hyperactivation state and subsequent severe COVID-19." (PMID 39811276, 2025). "Interestingly, many pro-inflammatory genes including S100A8 and S100A9, chemotaxis genes such as CXCR2 and FPR1, and NETosis-associated genes such as TIMP1 were highly expressed in neutrophils of ANPEP-high patients with COVID-19 compared with ANPEP-low patients with COVID-19." (PMID 40168094, 2025). "Also, in allelic comparison, CXCR2- neither T or C allele was found to be significantly associated with susceptibility to COVID-19 (OR = 1.13, RR=1.06 and p = 0.810)." (PMID 38544825, 2024). "The risk of susceptibility to COVID-19 was significantly associated with TNF-α rs1800629 GA, GA+AA genotypes and the A allele, IL-8 rs4073 TA, AA genotypes and A allele, IL-10 rs1800872 GA and CC genotypes and C allele, and CXCR2 rs2230054 CT and CT+CC genotypes." (PMID 38544825, 2024). "In patients with moderate COVID-19, there was a significant upregulation of L-selectin (SELL/CD62L) and C-X-C Motif Chemokine Receptor 2 (CXCR2), indicating an activated state aimed at moderate inflammation control and pathogen clearance." (PMID 39928675, 2025). "We observed that certain markers (CXCR4, CXCR2, CD63, and LOX-1) showed a correlation with COVID-19 disease severity." (PMID 39253969, 2024). "For CD4+ T cells, an increase in frequencies of CXCR2+ CD74+ cells was found in both mild and severe COVID-19 compared to healthy controls (mean: healthy: 17.7%, mild 46.9%, severe 42.9%)." (PMID 37946732, 2023). "This expression can make T lymphocytes more susceptible to MIF signaling and to CD74-dependent activation, since also the signaling coreceptor molecules CXCR2 and CXCR4 were enhanced on T cells in COVID-19 patients." (PMID 37946732, 2023). "Our results suggest that increased CXCR1, CXCR2, Mac-1/CD11b and L-selectin on CD16+ monocytes contribute to the immunopathogenesis of severe COVID-19 by increasing transmigration of these monocytes into tissues, including the lung." (PMID 34108966, 2021). "In contrast, the expression of CXCR2 on CD74+ Tregs (mean: healthy 15.9%, mild 37.5%, severe 42.4%) as well as on CD74+ convCD4+ T cells (mean: healthy 16.3%, mild 42.1%, severe 39.1%) was enhanced in COVID-19 patients." (PMID 37946732, 2023).
COVID-19 (continued). "For all chemokine receptors except CXCR2 a lower expression was observed on non-naïve T cells in COVID-19 patients." (PMID 35371005, 2022). "In addition, we found that CD16+ monocytes from people with severe COVID-19 had upregulated CXCL8 receptor genes, CXCR1 and CXCR2, compared to mild cases." (PMID 34108966, 2021). "Furthermore, upon bacterial challenge, a similar pattern of cell surface receptor phenotype with reduced expression of CXCR1, CXCR2, CXCR3, CCR1, CCR5 and the maturation marker CD15, with increased expression of CXCR4 and CD66b was found in neutrophils from acute-phase COVID-19 patients." (PMID 35007290, 2022). "Furthermore, there are no registered trials of CXCR2 inhibitors for the treatment of COVID-19 patients." (PMID 35697684, 2022). "Population 1 (CD16+CD10+CD63hiCD62L–PD-L1–) was predominantly enriched in 1 healthy donor and virtually absent in others, whereas population 6 (CD16+CD10+CD62L+CXCR2+CXCR4–), which contained CD16+CD10+ cells, was underrepresented in COVID-19." (PMID 39253969, 2024). "As regards the chemokine receptors, CXCR2 and CXCR4, we found significantly reduced levels of CXCR4 in severe COVID-19 patients and only a non-significant trend of reduction for CXCR2." (PMID 37568438, 2023). "Last, expression of CXCR2 and CXCR4, which define neutrophil maturation stages and regulate their trafficking from bone marrow, was detected in the two neutrophil clusters identified in patients with COVID-19 (aged and nonaged neutrophils)." (PMID 33622974, 2021).
glioblastoma (36 papers, 2012 to 2025). The most malignant astrocytic tumor (WHO grade IV). "This underlines the importance of the CXCR2 axis bypassing the VEGF-mediated angiogenesis pathways in the development of therapy resistance in human glioblastoma." (PMID 33807899, 2021). "A previous study showed that the tumour cells expressing CXCR2 drive vascular mimicry in antiangiogenic glioblastoma." (PMID 41446394, 2025). "Differential expression patterns of CD74 and CXCR2 by MDSCs within and outside the glioblastoma TME further emphasize that MIF signaling is location-specific." (PMID 39233830, 2024). "CXCR1- and CXCR2 modified CD70 engineered CAR T cells demonstrated increased intratumoral infiltration in glioblastoma in an in vivo model." (PMID 39835140, 2024). "In a preclinical study, CXCR2-expressing cancer cells were found to drive resistance to antiangiogenic therapy in glioblastoma." (PMID 36980182, 2023). "Recently, besides VEGF, an alternative angiogenic signaling pathway via CXCL2/CXCL8 and its receptor CXCR2 was identified as an essential part of angiogenesis in glioblastoma." (PMID 35269652, 2022). "VM was associated with high expression of HIF-1α and upregulation of the IL-8/CXCR2 pathway (implicated in glioblastoma stemness), sustaining the formation of functional PAS-positive channels lined by CXCR2+ tumor cells." (PMID 33921099, 2021). "Therapeutic stress increases CXCL8 and CXCR2 expression, enhancing glioblastoma tumorigenicity, growth, and therapy resistance by inducing glioma-initiating cell formation." (PMID 35011369, 2021). "We demonstrate the impact of CXCR2 signaling on endothelial cells supporting an impact of this pathway in angiogenesis of glioblastoma." (PMID 33807899, 2021). "CAR-T cells armed with CXCL8 receptors (CXCR1 and CXCR2) markedly enhanced T cells infiltration and led to complete antitumor responses in murine models ovarian cancer, pancreatic cancer, and glioblastoma." (PMID 33381115, 2020). "An unbiased angiogenesis-specific antibody array screen identified the chemokine, interleukin-8, which was further demonstrated to function as a key factor involved in glioblastoma-induced permeability, mediated through its receptor CXCR2 on brain endothelia." (PMID 23029099, 2012). "More specifically, these data suggest that glioblastoma-derived IL-8 signals to brain microvascular endothelial cells via CXCR2, which promotes remodeling of VE-cadherin-mediated cell-cell junctions and increases permeability." (PMID 23029099, 2012). "We hypothesized the existence of a proliferative signaling loop involving CXC chemokines (e.g., CXCL1 and CXCL8) and their receptors (e.g., CXCR1 and CXCR2) in glioblastoma growth." (PMID 40362634, 2025). "For example, increased expression of CXCL5 in the tumor microenvironment has been linked to activation of the CXCR2 pathway and recruitment of pro-tumor immune cells, thereby promoting tumorigenesis and angiogenesis, demonstrating that CXCL5 expression drives glioblastoma progression." (PMID 41387890, 2025). "In addition, glioblastoma multiforme tumors contain CXCR2+ cancer stem cells, cells that exhibit vascular mimicry due to their ability to incorporate into forming blood vessels." (PMID 40427171, 2025). "Notably, both CXCL3 and CXCL5 were identified as hub genes, indicating the significant involvement of the CXCR2 signaling pathway in the progression of glioblastoma." (PMID 38365809, 2024). "However, CXCR2 antagonist treatment reduced chemokines and the sprouting of endothelial cells, proving the impact of this pathway in the glioblastoma angiogenic course." (PMID 36980182, 2023). "In addition, we have previously demonstrated that blocking of IL-8 receptor CXCR2 or depletion of Gal-8 in tumor cells inhibits NO signaling mediated by conditioned medium from glioblastoma and breast tumor cells." (PMID 37773178, 2023).
glioblastoma (continued). "Also, an in vitro experiment, performed on a glioblastoma cell line, revealed that cellular migration was reduced when the CXCR2-specific inhibitor SB225002 was applied." (PMID 35269652, 2022). "Glioblastoma cell-secreted CXCL8 induced brain endothelial cell permeability via CXCR2." (PMID 34638514, 2021). "However, further studies are warranted to fully understand the impact of the CXCL2/IL8/CXCR2 axis on glioblastoma as well as the possible role of interference with this signaling in future therapy approaches." (PMID 33807899, 2021). "CXCL8 and CXCL2 enhance angiogenesis through CXCR2 signaling on endothelial cells in glioblastoma." (PMID 35011369, 2021). "It has been suggested that this may be related to VM, the alternative mechanism for glioblastoma to form new blood vessels in which CXCR2 may play a significant role." (PMID 34200145, 2021). "Overall, all the experiments performed support the concept that autocrine CXCL8-CXCR1/CXCR2 signalling plays a key role in the activation of an aggressive phenotype in glioblastoma cells, this effect is conserved both in U-87MG cell lines and in primary culture isolated from GB patient specimen." (PMID 31986121, 2020). "This dichotomy in the expression of IL-8 and its receptor CXCR2 might explain how glioblastoma cells regulate brain endothelium properties." (PMID 23029099, 2012). "Therefore, our duet culture model provides evidence that glioblastoma-produced IL-8 elicits a pro-permeability and pro-angiogenic response through its endothelial receptor CXCR2." (PMID 23029099, 2012). "Additionally, CXCR2, the physiological receptor for CXCL8 has been shown to improve CAR T cell therapy preclinically, now being tested in a phase 1 study targeting glioblastoma (NCT05353530) where an anti-CD70 CAR T cell is additionally modified to express CXCR2." (PMID 36366354, 2022). "Thus, the CXCL2/IL8/CXCR2 axis could be a relevant pathway to circumvent the disturbance of the VEGF/VEGFR signaling in glioblastomas to maintain tumor angiogenesis." (PMID 33807899, 2021). "The release of CXCL2 activated CXCR2 and the blockade of CXCR2 signaling hindered macrophage-like cell migration that was triggered by programmed cell death 10 (PDCD10)-overexpressed glioblastoma cells." (PMID 39007996, 2024). "Starting from these evidences, in this work we first examined the expression of CXCR1/CXCR2 and secreted CXCL8 in human glioblastoma U-87MG cell line and primary cell cultures from post-surgical specimens of glioblastoma patients." (PMID 31986121, 2020). "Previous literature points to a specific expression of CXCR1 and lack of CXCR2 expression in GB cell lines, although we observed that glioblastoma cells also express CXCR2." (PMID 31986121, 2020). "Moreover, enhanced levels of IL-8 and its receptors CXCR1 and CXCR2 enhanced CSC migration, growth and stemness properties in glioblastoma." (PMID 27259257, 2016). "In oesophageal squamous cell carcinoma (ESCC) and glioblastoma (GBM), SRGN can indirectly upregulate the expression of MMP2/MMP9 by activating the ERK pathway, TGF‐β signalling, or the CXCLs/CXCR2 axis, thereby enhancing tumour invasion and metastasis." (PMID 41410182, 2025). "As shown in our previous results, PDCD10 participates in the crosstalk between glioblastoma cells and microglia/macrophages and promotes tumor growth by CXCL2-CXCR2 signaling in vivo, which suggests that CXCR2 may play a critical role in aggressive behaviors mediated by PDCD10 in tumors." (PMID 35963638, 2022). "Therefore, IL-8, but not CXCR2 expression, might contribute to glioblastoma aggressiveness and high vascularity in human patients." (PMID 23029099, 2012).
glioma (32 papers, 2012 to 2025). A benign or malignant brain and spinal cord tumor that arises from glial cells (astrocytes, oligodendrocytes, ependymal cells). "Enhanced expression of CXCR2 and its ligands is associated with malignancy and recurrence in glioma." (PMID 34203660, 2021). "CXCR-2 pathway seems also to be an important regulator of the behavior of stromal cells in the glioma tumor microenvironment, including microglia and endothelial cells." (PMID 38672477, 2024). "The binding of CXC-motif chemokine receptor 2 (CXCR2) by its ligand CXCL2 provides an alternative signaling pathway to induce angiogenesis in gliomas via activation of immune host cells and independently of VEGF signaling." (PMID 37626776, 2023). "In the in vivo model created by injecting GL261 glioma cells, CXCR2-blocking by SB225002 notably reduced tumor volume by around 50%." (PMID 36980182, 2023). "There are many other proteins with pro-angiogenic activity currently under investigation in gliomas, such as the transmembrane protein vasorin, Ras homolog family member 1 (Rho1), and chemokine receptor 2 (CXCR2), along with its ligand CXCL2." (PMID 37626776, 2023). "It has been shown that blocking CXCR2 in an experimental glioma model resulted in a reduction in tumor volume by up to 50%, along with a reduction in invasiveness and lower tumor vessel density." (PMID 37626776, 2023). "In particular, CXCR2 overexpression was directly related to poor prognosis and recurrence in human glioma." (PMID 36980182, 2023). "Treatment with a CXCR2-antibody during initial tumor growth of the CXCL2-CXCR2 signaling pathway revealed significantly diminished volumes of glioma in transgenic mice." (PMID 35269652, 2022). "Circ-0000215 acts as a competitive endogenous RNA by sponging miR-495-3p, increasing glioma growth via the CXCR2 axis." (PMID 35883576, 2022). "The significance of up-regulated interleukin-8 (IL-8/CXCL8) and its receptors (CXCR1, CXCR2) levels in glioma was explored by many researcher groups." (PMID 35269652, 2022). "The expression of CXCR2 proteins in gliomas has been significantly correlated with glioma recurrence." (PMID 35860278, 2022). "In our previous study, we showed that the local treatment by CXCR2 antagonist SB225002 (SB) significantly reduced the TAM infiltration in an orthotopic glioma mouse model in vivo." (PMID 34681839, 2021). "Experimental data indicate that CCR5 and CXCR2 are involved in glioma cell invasion through tridimensional environments, when induced by co-cultured human mesenchymal stem cells or endothelial cells that were shown to secrete key chemokines." (PMID 35008294, 2021). "CXCR2 is expressed by a variety of cell types, e.g., endothelial cells, glioma cells, T lymphocytes, mast cells and myeloid cells." (PMID 33807899, 2021). "CXCL8 and CXCR2 tumor expression is related to glioma grade, disease-free survival, and OS in GBM, and their upregulation in high-grade glioma correlates with resistance to anti-angiogenic therapy." (PMID 34638384, 2021). "In fact, depleting the tumor of microglia or blocking CXCR2 on endothelial cells, significantly reduced glioma volume." (PMID 33066172, 2020). "We also found that incubating NETs-primed glioma cell CM or recombinant IL-8 with freshly isolated neutrophils resulted in NETs formation, and this effect was suppressed by inhibition of CXCR2 or the PI3K/AKT/ROS axis." (PMID 32296583, 2020). "The expression of CXCR2 was also significantly related to high grades of glioma and the recurrence of tumors." (PMID 32456359, 2020). "The proangiogenic activity of CXCL8 in gliomas is mainly related to CXCR2, which binds to all of the CXC ELR (+) chemokines." (PMID 32456359, 2020). "Altogether, our data converge on the idea of a glioma secreted-IL-8/endothelial CXCR2 dialogue in hCMEC/D3 permeability." (PMID 23029099, 2012). "The protein levels of CXCR-2 are in line with the degree of malignancy of gliomas and recurrence and could possibly be used as a therapeutic target." (PMID 38672477, 2024).